CPT1A (carnitine palmitoyltransferase 1A)
Diseases named in the same sentence as CPT1A in open-access papers (continued):
Sharing a sentence is not in itself a finding about the gene and the disease.
cervical (1 paper, 2024). "In this study, the molecular mechanisms of TM7SF2 via CPT1A in the process of cervical tumorigenesis were explored." (PMID 38693136, 2024). "Furthermore, whether WNT/β-catenin signaling pathway participated in TM7SF2 mediated cervical tumorigenesis via CPT1A was explored." (PMID 38693136, 2024).
cholestasis (1 paper, 2022). Impairment of the bile flow caused by obstruction within the liver, or outside the liver in the bile duct system. "PRR could reverse the abnormal changes of Cpt1a, Acat2, Ehhadh, and Hadha, among which Cpt1a, Ehhadh, and Hadha are fatty acid β-oxidation genes, indicating that fatty acid β-oxidation might play important role in the treatment of cholestasis by PRR." (PMID 36339580, 2022).
chondrosarcoma (1 paper, 2021). A malignant cartilaginous matrix-producing mesenchymal neoplasm arising from the bone and soft tissue. "Interestingly, chondrosarcomas with high expression levels of two regulators of acylcarnitine metabolism, CPT1A and FASN, displayed worse patient outcome." (PMID 33762012, 2021).
chronic kidney failure (1 paper, 2024). "Reduced expression of Cpt1A in patients with chronic kidney failure is associated with fibrosis." (PMID 38256023, 2024). "Cpt1A agonists are potential drugs for targeting the energy substrate selection stage to improve fibrosis in chronic kidney failure." (PMID 38256023, 2024).
chronic myeloid leukemia (1 paper, 2024). "In addition, the specific reasons and mechanisms for the low expression of CPT1A in chronic myeloid leukemia are still unclear." (PMID 39596847, 2024).
colitis (1 paper, 2026). Inflammation of the colon. "CPT1A downregulation exerts protective effects on DSS-induced colitis by suppressing PPARα signaling while also modulating PINK1-mediated mitophagy and reducing cellular ROS generation, thereby alleviating tissue damage induced by oxidative stress." (PMID 41563994, 2026).
colon adenocarcinoma (1 paper, 2024). "Further exploration of CPT1A expression in TCGA revealed that CPT1A mRNA levels were significantly lower in colon adenocarcinoma (COAD) tissues than in the adjacent non-tumour tissues." (PMID 39607749, 2024).
congestive heart failure (1 paper, 2021). Failure of the heart to pump a sufficient amount of blood to meet the needs of the body tissues, resulting in tissue congestion and edema. "For example, etomoxir, an irreversible inhibitor of CPT1A, has been demonstrated to have pharmacological effects with the capability to treat conditions such as congestive heart failure, although its clinical effectivity remains to be studied." (PMID 34944922, 2021).
dilated cardiomyopathy (1 paper, 2025). Cardiomyopathy which is characterized by dilation and contractile dysfunction of the left and right ventricles. "Indeed, hypertrophic and dilated cardiomyopathy are frequent findings in patients with deficiencies at the level of CACT, CPT2, VLCAD, and LCHAD/MTP, but not CPT1A, which follows logically from the fact that CPT1B and not CPT1A is the predominant CPT expressed in heart muscle." (PMID 38693715, 2025).
dry eye (1 paper, 2022). "In our previous study we found CPT1A, the rate-limiting enzyme of FAO, was downregulated in cornea of a dry eye model induced by sleep deprivation." (PMID 36588740, 2022).
E. coli infection (1 paper, 2018). "Cpt1a protein levels, detected by Western blotting, were similar in un-infected Mkp-1+/+ and Mkp-1−/− mice, and E. coli infection caused a significant decrease in both Mkp-1+/+ and Mkp-1−/− mice." (PMID 30563203, 2018). "Cpt1a mRNA expression was significantly decreased in both Mkp-1+/+ and Mkp-1−/− mice upon E. coli infection, although expression levels in control conditions were similar in the two genotypes of mice." (PMID 30563203, 2018).
esophageal cancer (1 paper, 2022). A primary or metastatic malignant neoplasm involving the esophagus. "The role of CPT1A-mediated FAO in the context of promoting cell growth has been described in other cancers, but not in esophageal cancer." (PMID 36233047, 2022).
experimental autoimmune encephalomyelitis (1 paper, 2019). An autoimmune demyelinating disease of the central nervous system that is produced experimentally in animals by the injection of homogenized brain or spinal cord in Freund's adjuvant. "To elucidate the role of CPT1A, we established a Cpt1a P479L mouse strain and evaluated its sensitivity to experimental autoimmune encephalomyelitis (EAE) induction." (PMID 31527712, 2019).
fibrosarcoma (1 paper, 2018). A malignant mesenchymal fibroblastic neoplasm affecting the soft tissue and bone. "In human UPS and fibrosarcoma CPT1A is modestly elevated or unchanged relative to normal tissues, whereas muscle-specific CPT1B is lost and FASN is increased." (PMID 30382078, 2018).
gestational diabetes (1 paper, 2025). Carbohydrate intolerance first diagnosed during pregnancy. "CPT1A (2 sites) is associated with an increased risk of gestational diabetes mellitus (GDM)." (PMID 39827095, 2025).
gout (1 paper, 2021). A condition characterized by painful swelling of the joints, which is caused by deposition of urate crystals. "The CPT1A hypomethylation observed here therefore likely promotes gout by increasing CPT1A expression and IL-1β production in macrophages." (PMID 33493135, 2021). "The final nine surviving monocyte-specific differentially methylated CpG sites were mapped to eight genes (PRKCZ, CIDEC, VDAC1, CPT1A, BIRC2, BRCA1, STK11, and NLRP12) that have not previously been studied in the field of gout genetics." (PMID 33493135, 2021).
Hashimoto thyroiditis (1 paper, 2025). An autoimmune disorder caused by the production of autoantibodies against thyroid tissue. "The mTOR/ACC1/CPT1A fatty acid oxidation pathway of CD4+T cells in Hashimoto’s thyroiditis was increased, and treatment with Etomoxir could inhibit the activation of this pathway, and reverse the reprogramming of abnormal metabolism in CD4+T cells, thereby reducing Hashimoto’s thyroiditis." (PMID 39641893, 2025).
Hereditary breast cancer (1 paper, 2022). Breast carcinoma that has developed in relatives of patients with history of breast carcinoma. "There are also associations of CPT-1A with the wild-type variants of moderate to highly penetrant genes e.g. BRCA1, BRCA2 and ATM involved in hereditary breast cancer." (PMID 36180554, 2022).
inflammatory bowel disease (1 paper, 2022). A spectrum of small and large bowel inflammatory diseases of unknown etiology. "Importantly, loss of carnitine palmitoyl transferase 1a (CPT1a—a rate-controlling enzyme of FAO) results in EC dysfunction in vivo and promotes LPS-induced vascular inflammation and inflammatory bowel disease in mice." (PMID 36232355, 2022).
insulinoma (1 paper, 2025). "For example, inhibition of CPT1A with etomoxir produced an increase in insulin secretion in insulinoma cells, and conversely, when CPT1A was overexpressed in insulinoma cells, GSIS was decreased." (PMID 39814231, 2025).
invasive ductal carcinoma (1 paper, 2021). "Relative to in situ cancer cases (training set: 31.17 ± 18.35 ng/mL; test set: 31.20 ± 25.37 ng/mL), invasive ductal carcinoma cases exhibited higher CPT1A levels (training set: 41.21 ± 36.66 ng/mL, p < 0.001; test set: 37.90 ± 42.91 ng/mL, p < 0.001)." (PMID 33858374, 2021).
ischemic disease (1 paper, 2018). Lack of blood supply to an area of the body, resulting in impairment of tissue oxygenation. "DQP, on the other hand, serves as an agonist of CPT1A and can be used to promote angiogenesis for ischemic diseases." (PMID 30564122, 2018). "Our study suggested that pharmacological activation of CPT1A might provide an alternative for therapeutic angiogenesis in the treatment of ischemic diseases." (PMID 30564122, 2018).
lipidosis (1 paper, 2022). "In addition, we first reported that ssc-miR-133a-3p, ssc-miR-486 and ssc-miR-1 regulate the target genes CPT1A, SCD5 and SCD, respectively, in the PPAR signaling pathway so that they can have an impact on lipidosis." (PMID 36672834, 2022).
liver cirrhosis (1 paper, 2023). "For instance, CPT1A, a FAM-related gene, was reported to be critical in the activation of hepatic stellate cells and was implicated in the development of liver cirrhosis via fatty acid oxidation." (PMID 36671526, 2023).
Luminal breast cancer (1 paper, 2016). "A recent report showed that the CPT1A gene is amplified and presents as a genetic driver of proliferation in Luminal breast cancer." (PMID 27563814, 2016).
lung diseases (1 paper, 2024). "CPT1A, an active form of the CPT1 system, is deeply involved in the biology of many lung diseases, such as ALI, chronic obstructive pulmonary disease, and bronchial asthma." (PMID 39090662, 2024).
lymphopenia (1 paper, 2020). Reduction in the number of lymphocytes. "This global increase could be driven by lymphopenia-associated IL-15 signaling, as IL-15 is known to promote CPT1a expression and FAO engagement and promote mitochondrial biogenesis." (PMID 33013907, 2020).
malnutrition (1 paper, 2021). Inadequate nutrition resulting from poor diet, malabsorption, or abnormal nutrient distribution. "The findings from the Dutch Famine cohort has shown the positive correlation between prenatal malnutrition and methylation within a Cpt1a enhancer." (PMID 33799409, 2021).
mastitis (1 paper, 2024). Inflammation of breast tissue during lactation or postpartum due to an obstructed duct or infection. "A previous study identified upregulated expression of CPT1A in response to intra-mammary lipopolysaccharide challenge, which agrees with its upregulation in milk somatic cells during S. aureus subclinical mastitis in this study." (PMID 38486242, 2024).
MCAD deficiency (1 paper, 2018). "Plasma C14:1 and C14:2 were elevated in VLCAD deficiency, C14OH, C16OH and C18:1OH levels in LCHAD/MTP deficiencies, C6 and C8 in MCAD deficiency, C2 and C4 in SCAD deficiency, and C0/(C16 + C18) in CPT1A deficiency." (PMID 29519241, 2018). "Germline mutations of the gene responsible for each FAOD were identified in 90% of alleles (9 out of 10 alleles) in VLCAD deficiency, 90% (9 out of 10 alleles) in MCAD deficiency, 100% (2 out of 2 alleles) in LCHAD/MTP, primary carnitine, CPT1A, and SCAD deficiencies." (PMID 29519241, 2018).
meningioma (1 paper, 2025). A generally slow growing tumor attached to the dura mater. "FAO, with adjuvant CPT1a inhibitors, may restore ferroptosis vulnerability in NOTCH3 expressing meningiomas." (PMID 40502769, 2025).
metastatic colorectal cancer (1 paper, 2021). "In our study, the proteomic, RT‐qPCR, IHC, and database analyses highlighted that the expression of CPT1A was low in patients with peritoneal metastatic colorectal cancer and was associated with shorter overall survival." (PMID 33528867, 2021).
mucinous carcinomas (1 paper, 2022). "Clustering of CPT-1A with immune pathways in the context of underexpression occurs in tubular and mucinous carcinomas, both carcinomas which are associated with a good prognosis." (PMID 36180554, 2022). "Likewise, with the good prognostic histological subtypes, tubular and mucinous carcinomas, there was a tendency for CPT-1A to cluster in the context of under expression." (PMID 36180554, 2022).
mucinous ovarian cancer (1 paper, 2023). An invasive malignant neoplasm that arises from the ovary and is characterized by the presence of malignant epithelial cells that contain intracytoplasmic mucin and may resemble the epithelial cells of the endocervix or gastrointestinal tract. "Meanwhile, the results also showed that, similar to CPT1A, MFF had a higher IHC score for protein expression in endometrioid and mucinous ovarian cancers." (PMID 37291333, 2023).
myocarditis (1 paper, 2022). Myocarditis is a condition that is characterized by inflammation of the heart muscle (myocardium). "Also, we confirmed not only PDK4, but also CPT1A and ACSL1, which are known to be key regulators of fatty acid metabolism, are the target transcripts of CEBPB in classical monocytes in BNT162b2-myocarditis." (PMID 36225942, 2022).
nosocomial infection (1 paper, 2024). An infection acquired in a hospital or other healthcare setting. "Based on the results from MDS analyses, we focused the analyses evaluating the association between nosocomial infection occurrence and NK cell-specific CPT1a and NRF1 expression." (PMID 38426112, 2024). "The findings consistently showed that the risk of nosocomial infection is associated with increased CPT1a in all NK cell subsets, NKT cells, and some T lymphocyte subsets." (PMID 38426112, 2024). "In conclusion, our findings shed light on the role of perturbed NK cell immunometabolism, including NRF1 downregulation and CPT1a upregulation, in the risk of nosocomial infection in CCI." (PMID 38426112, 2024). "Notably, downregulation of intracellular NRF1 in the NK cell population and subpopulations was significantly associated with an increased risk of nosocomial infection, whereas CPT1a was upregulated in all NK cell subpopulations from patients who developed nosocomial infection." (PMID 38426112, 2024). "Here, through unbiased exploration, we uncovered the association between NK cell-specific immunometabolism, in particular the altered expression of NRF1 and CPT1a, and nosocomial infection in patients with CCI." (PMID 38426112, 2024). "Collectively, our results revealed that NK cells were the predominant immune cell type, and CPT1a and NRF1 were the principal metabolic regulators associated with the risk of nosocomial infection." (PMID 38426112, 2024). "This analysis indicated that CPT1a and NRF1 expression levels in NK cell subsets and plasma IL-15 levels are strongly associated with nosocomial infection risk." (PMID 38426112, 2024). "Downregulated NRF1 and upregulated CPT1a were found in all subsets of NK cells from patients who developed a nosocomial infection." (PMID 38426112, 2024). "Compared to subjects without nosocomial infection, those with nosocomial infection exhibited an increased abundance of a specific cluster which is characterized by elevated CPT1a expression and reduced NRF1 expression." (PMID 38426112, 2024).
Oral Cancer (1 paper, 2024). "Reports on the association between the oral microbiome and oral cancer are limited; the role of CPT1A as a regulator of fatty acid metabolism with relevance to the oral microbiome and oral cancer risk has rarely been investigated." (PMID 39456670, 2024). "Our findings confirm that CPT1A is a lipid-metabolism regulator associated with oral cancer." (PMID 39456670, 2024). "Oral cancer tissues showed significantly elevated levels of the CPT1A protein; an increased presence of T-helper cell counts (CD4+); and higher levels of OXSR1, IL-6, and TNF-α." (PMID 39456670, 2024). "In contrast, oral cancer patients demonstrated elevated concentrations of key markers, including CPT1A, IL-6, OXSR1, and TNF-α, reflecting substantial alterations in metabolic and inflammatory pathways." (PMID 39456670, 2024). "Patients with oral cancer exhibited notable changes in enzymes critical for fatty acid metabolism, particularly CPT1A, while healthy controls had higher levels of short-chain fatty acids (SCFAs) and CD4+T-helper cell counts." (PMID 39456670, 2024). "In conclusion, our findings reveal a potential association between oral microbiome dysbiosis and metabolic enzymes, such as CPT1A, alongside immunological pathways in oral cancer." (PMID 39456670, 2024). "We investigated whether a synergistic interaction between the oral microbiome and underlying metabolic pathways, particularly involving enzymes such as carnitine O-palmitoyltransferase 1 (CPT1A), plays a key role in oral cancer." (PMID 39456670, 2024). "Our findings highlight the crucial role of the oral microbiome in regulating key metabolic enzymes, such as CPT1A and OXSR1, as well as cytokines like TNF-α and IL-6 in oral cancer." (PMID 39456670, 2024).
osteoporosis (1 paper, 2017). A condition of reduced bone mass, with decreased cortical thickness and a decrease in the number and size of the trabeculae of cancellous bone (but normal chemical composition), resulting in increased fracture incidence. "Further functional study on the molecular mechanism of CPT1A, MTL5 gene and LRP5 rs3736228 may help us comprehend the association between osteoporosis and candidate gene, understand the pathogenesis of osteoporosis and the genetic mechanism." (PMID 28369098, 2017). "All of the functional evidence suggested the important functional mechanisms underlying the associations of the 2 SNPs (rs2278729 and rs3736228) and 3 genes (RPL31, CPT1A and MTL5) with osteoporosis." (PMID 28369098, 2017).
osteosarcoma (1 paper, 2022). A usually aggressive malignant bone-forming mesenchymal neoplasm, predominantly affecting adolescents and young adults. "According to our results, high expression of CPT1A suggests that fatty acid beta oxidation may play an important role in osteosarcoma metabolism." (PMID 35392503, 2022).
otitis (1 paper, 2022). "Interestingly, supporting a role for FAO and CPT1a in shaping an efficient long-lasting immune response, a study of Native Alaskan children carrying a hypomorphic variant of CPT1a showed a higher incidence of respiratory tract infection and otitis in comparison with the control group." (PMID 34981777, 2022).
ovarian serous carcinoma (1 paper, 2016). "The results indicated that CPT1A protein is present abundantly in a high proportion of ovarian serous carcinomas." (PMID 26716645, 2016).
pancreatitis (1 paper, 2025). Inflammation of the pancreas. "While the role of CPT1A in promoting FAO is well-known, the exact molecular mechanisms underlying its protective effects in pancreatitis remain largely unexplored." (PMID 40718711, 2025).
periodontal disease (1 paper, 2025). "Additionally, previous studies have documented that the activation of the MAPK signaling pathway in various immune cells modulates the progression of periodontal disease and the loss of alveolar bone, suggesting that CPT1A is involved in the inflammatory response of macrophages in vitro." (PMID 40606607, 2025).